ENSG00000214265 (novel protein)
Gene: Protein-coding gene on chromosome 15 (24,955,034 to 25,000,276, forward strand). Ensembl gene ENSG00000214265.
Genetic constraint (gnomAD): Missense variants: 84 observed, 92.07 expected, observed/expected ratio (o/e) 0.91, 90% interval 0.76 to 1.09. Synonymous variants: 29 observed, 33.58 expected, observed/expected ratio (o/e) 0.86, 90% interval 0.64 to 1.18.